RNU6-642P (RNA, U6 small nuclear 642, pseudogene)
Gene: Small nuclear RNA gene on chromosome 2 (218,916,184 to 218,916,287, reverse strand). Ensembl gene ENSG00000200029.
Homologues: Paralogues in human: RNU6-43P (90% identical), RNU6-140P (89% identical), RNU6-398P (89% identical), RNU6-422P (89% identical), RNU6-97P (88% identical), RNU6-24P (88% identical), RNU6-454P (88% identical), RNU6-536P (88% identical), RNU6-11P (87% identical), RNU6-1216P (87% identical), RNU6-1243P (87% identical), RNU6-1310P (87% identical), and 1290 more.